OR13G1 (olfactory receptor family 13 subfamily G member 1)
Description:
Odorant receptor.
Synonyms: OR1-37
Tractability: Antibody: UniProt places it where antibodies can reach, with medium confidence; UniProt predicts a signal peptide or a membrane-spanning region; its Gene Ontology location is reachable by antibodies, with medium confidence.
Gene: Protein-coding gene on chromosome 1 (247,670,812 to 247,679,739, reverse strand). Ensembl gene ENSG00000197437.
Subcellular location: Cell membrane
Pathways (Reactome):
Sensory Perception: Expression and translocation of olfactory receptors
Gene Ontology:
Molecular function: odorant binding; olfactory receptor activity; G protein-coupled receptor activity
Biological process: detection of chemical stimulus involved in sensory perception of smell; G protein-coupled receptor signaling pathway
Cellular component: membrane; plasma membrane
Genetic constraint (gnomAD): Loss-of-function variants: 0 observed, 0.27 expected, observed/expected ratio (o/e) 0, 90% interval 0 to 1.87. That is too few expected variants to judge how well the gene tolerates losing a copy. Missense variants: 369 observed, 407.43 expected, observed/expected ratio (o/e) 0.91, 90% interval 0.83 to 0.99. Synonymous variants: 128 observed, 144.7 expected, observed/expected ratio (o/e) 0.88, 90% interval 0.76 to 1.02.
Homologues: Orthologues: macaque OR13G1 (97% identical), chimpanzee OR13G1 (93% identical), rat Or13g1 (86% identical), mouse Or13g1 (85% identical), pig OR13G1 (84% identical), guinea pig OR13G1 (83% identical), dog OR13G1 (82% identical). Paralogues in human: OR1J2 (42% identical), OR1L1 (42% identical), OR1L3 (42% identical), OR1F1 (41% identical), OR4A15 (41% identical), OR4S2 (41% identical), OR1J1 (41% identical), OR1J4 (41% identical), OR1L8 (41% identical), OR4C15 (41% identical), OR4C45 (41% identical), OR1C1 (41% identical), and 116 more.
Diseases named in the same sentence as OR13G1 in open-access papers:
OR13G1 is named in the same sentence as 2 diseases in open-access papers, as found by Europe PMC text mining. Sharing a sentence is not in itself a finding about the gene and the disease. The quoted sentences say what the papers report.
myocardial infarction (1 paper, 2010). Gross necrosis of the myocardium, as a result of interruption of the blood supply to the area, as in coronary thrombosis. "As with the TAS2R50 bitter receptor gene, a single nucleotide polymorphism in the OR13G1 (olfactory receptor, family 13, subfamily G, member 1) gene has been linked with an increased risk of myocardial infarction." (PMID 20352025, 2010).
OR13G1 also shares sentences with these, for which no sentence is quoted: head and neck cancer (1 paper).